ENSG00000276229
Gene: Miscellaneous RNA gene on chromosome 2 (44,935,294 to 44,935,368, forward strand). Ensembl gene ENSG00000276229.
Gene Ontology:
Biological process: regulation of gene expression
Homologues: Orthologues: mouse Gm55783 (83% identical).